MTERF2 (mitochondrial transcription termination factor 2)
Description:
Binds mitochondrial DNA and plays a role in the regulation of transcription of mitochondrial mRNA and rRNA species.
Synonyms: mTERFL; MTERFD3; FLJ14062
Tractability: PROTAC: ubiquitination databases record sites on it; its protein half-life has been measured.
Gene: Protein-coding gene on chromosome 12 (106,973,120 to 106,987,173, reverse strand). Ensembl gene ENSG00000120832.
Subcellular location: Mitochondrion; Mitochondrion matrix, mitochondrion nucleoid
Gene Ontology:
Molecular function: DNA binding; protein binding; nucleic acid binding
Biological process: termination of mitochondrial transcription
Cellular component: mitochondrion; mitochondrial matrix; mitochondrial nucleoid
Genetic constraint (gnomAD): Loss-of-function variants: 23 observed, 31.76 expected, observed/expected ratio (o/e) 0.72, 90% interval 0.52 to 1.03. The upper end of that interval is the gene's LOEUF score, 1.03, which puts it in group 4 of 6, group 1 being the genes least tolerant of losing a copy. Missense variants: 440 observed, 454.62 expected, observed/expected ratio (o/e) 0.97, 90% interval 0.89 to 1.05. Synonymous variants: 157 observed, 169.37 expected, observed/expected ratio (o/e) 0.93, 90% interval 0.81 to 1.06.
Homologues: Orthologues: chimpanzee MTERF2 (99% identical), macaque MTERF2 (97% identical), dog MTERF2 (87% identical), rabbit MTERF2 (86% identical), pig MTERF2 (78% identical), mouse Mterf2 (76% identical), rat Mterf2 (76% identical), guinea pig MTERF2 (71% identical), tropical clawed frog mterf2 (49% identical), zebrafish mterf2 (46% identical), Drosophila melanogaster mTTF (16% identical). Paralogues in human: MTERF1 (26% identical).
Diseases named in the same sentence as MTERF2 in open-access papers:
MTERF2 is named in the same sentence as 4 diseases in open-access papers, as found by Europe PMC text mining. Sharing a sentence is not in itself a finding about the gene and the disease. The quoted sentences say what the papers report.
hemophagocytic lymphohistiocytosis (1 paper, 2021). "Mterf2 is involved in regulating mitochondrial mRNA and rRNA transcription, and Fhl4 mutations can lead to hemophagocytic lymphohistiocytosis." (PMID 34794440, 2021).
cancer (2 papers, 2021 to 2024). A tumor composed of atypical neoplastic, often pleomorphic cells that invade other tissues. "The regulatory network analysis revealed that ZNF10, a transcriptional repressor protein, was MTERF2’s potential target in 10 cancers." (PMID 34030708, 2021). "The MTERF family includes MTERF1, MTERF2, MTERF3, and MTERF4 that have roles in the pathogenesis of various cancer types." (PMID 38324544, 2024).
MTERF2 also shares sentences with these, for which no sentence is quoted: breast carcinoma (1 paper); tumor (1).